MESP2 (mesoderm posterior bHLH transcription factor 2)
Description:
Transcription factor with important role in somitogenesis. Defines the rostrocaudal patterning of the somite by participating in distinct Notch pathways. Also regulates the FGF signaling pathway. Specifies the rostral half of the somites. Generates rostro-caudal polarity of somites by down-regulating in the presumptive rostral domain DLL1, a Notch ligand. Participates in the segment border formation by activating in the anterior presomitic mesoderm LFNG, a negative regulator of DLL1-Notch signaling. Acts as a strong suppressor of Notch activity. Together with MESP1 is involved in the epithelialization of somitic mesoderm and in the development of cardiac mesoderm.
Synonyms: bHLHc6; SCDO2
Tractability: No criterion of Open Targets' tractability assessment is met for any kind of drug.
Gene: Protein-coding gene on chromosome 15 (89,760,591 to 89,778,754, forward strand). Ensembl gene ENSG00000188095.
Subcellular location: Nucleus
Pathways (Reactome):
Developmental Biology: Somitogenesis
Gene Ontology:
Molecular function: sequence-specific double-stranded DNA binding; DNA-binding transcription factor activity, RNA polymerase II-specific; RNA polymerase II cis-regulatory region sequence-specific DNA binding; DNA-binding transcription factor activity; protein dimerization activity
Biological process: heart morphogenesis; mesoderm formation; regulation of transcription by RNA polymerase II; somite rostral/caudal axis specification
Cellular component: chromatin; nucleus
Genetic constraint (gnomAD): Loss-of-function variants: 33 observed, 26.56 expected, observed/expected ratio (o/e) 1.24, 90% interval 0.94 to 1.66. The synonymous counts are far from expectation, so gnomAD's model fits this gene poorly and the ratio says little. Missense variants: 645 observed, 474.85 expected, observed/expected ratio (o/e) 1.36, 90% interval 1.27 to 1.45. Synonymous variants: 303 observed, 213 expected, observed/expected ratio (o/e) 1.42, 90% interval 1.29 to 1.56.
Homologues: Orthologues: chimpanzee MESP2 (96% identical), macaque MESP2 (87% identical), dog MESP2 (70% identical), pig MESP2 (65% identical), mouse Mesp2 (61% identical), rat Mesp2 (60% identical), guinea pig MESP2 (58% identical), tropical clawed frog mespb (20% identical), zebrafish mespbb (19% identical), tropical clawed frog mespa (18% identical), zebrafish mespba (18% identical), zebrafish mespab (17% identical), and 2 more. Paralogues in human: MESP1 (40% identical), MSGN1 (13% identical).
Diseases named in the same sentence as MESP2 in open-access papers:
MESP2 is named in the same sentence as 9 diseases in open-access papers, as found by Europe PMC text mining. Sharing a sentence is not in itself a finding about the gene and the disease. The quoted sentences say what the papers report.
spondylocostal dysostosis (6 papers, 2014 to 2025). Spondylocostal dysplasia is a rare genetic disorder characterized by defects of the bones of the spine (vertebrae) and abnormalities of the ribs. "Similarly, the other genes associated with recessive spondylocostal dysostosis (MESP2, LFNG, and HES7) have been associated with regulating Notch-signaling activity during somitogenesis." (PMID 36506336, 2022). "STD (known as Jarcho-Levin syndrome caused due to mutations in MESP2 gene is characterized by a short and rigid neck, short thorax, protuberant abdomen and inguinal and umbilical hernias, severe shortening of the spine with fusion of the ribs posteriorly at the costo-vertebral junctions." (PMID 24932600, 2014). "Human pathogenic alterations in MESP2 and HES7 cause spondylocostal dysostosis characterized by rib and vertebral abnormalities." (PMID 40259859, 2025).
autosomal recessive spondylocostal dysostosis (1 paper, 2020). "Similar with TBX6, biallelic loss‐of‐function variants in RIPPLY2 or MESP2 cause autosomal recessive Spondylocostal Dysostosis (MIM#616566 for RIPPLY2 and MIM#608681 for MESP2)." (PMID 32815649, 2020).
gastric tumor (1 paper, 2023). "Herein, we detected for the first time, a decline in MESP2 expression in gastric tumor tissues that were simultaneously negatively correlated with GC grade." (PMID 36854722, 2023). "MESP2 IHC staining was notably lower in gastric tumor tissues in a grade-dependent pattern compared to that in normal tissues." (PMID 36854722, 2023).
scoliosis (1 paper, 2025). A congenital or acquired spinal deformity characterized by lateral curvature of the spine. "Congenital scoliosis is largely characterized by mutations in developmental genes such as TBX6, DLL3, and MESP2 and components of the Notch, Wnt, and HOX pathways." (PMID 41153437, 2025).
spondylothoracic dysostosis (1 paper, 2024). "Human disorders caused by MESP2 are classified as SCDO2; most are more severe than SCDO1 and lead to a disorder primarily defined as spondylothoracic dysostosis." (PMID 38252118, 2024).
cancer (2 papers, 2023 to 2025). A tumor composed of atypical neoplastic, often pleomorphic cells that invade other tissues. "Based on these results, we present a new hypothesis that TCF4/beta-catenin signalling is controlled inhibited by MESP2, but becomes significantly activated in the carcinoma stage due to MESP2 loss." (PMID 36854722, 2023). "In this work, considering that MESP2 expression levels are reduced in GC tissues and cell lines, we focused on MESP2 regulation and function, which to our knowledge, are uninvestigated in cancer." (PMID 36854722, 2023). "Given that the impact of p27 can be disrupted in human cancers by excess proteolysis, C-terminal phosphorylation, or reduced translation, we found that deletion of MESP2 leading to p27 downregulation was due to SKP2-mediated ubiquitination through the proteasome pathway." (PMID 36854722, 2023). "Previous experiments have showed that aberrant expression of the bHLH transcription factor is related to tumorigenesis, suggesting that MESP2 may also participate in human cancer progression." (PMID 36854722, 2023). "Furthermore, we provided evidence for the potential anti-cancer application of MESP2 as a marker for targeted therapy involving TCF4/beta-catenin signalling." (PMID 36854722, 2023). "Nevertheless, the function of MESP2 in human cancers have not been characterized till date." (PMID 36854722, 2023).
tumor (1 paper, 2023). "We used a mouse xenograft model to verify the putative tumor suppressor role of MESP2 in vivo, and discovered that knockdown of MESP2 promoted tumor growth and volume." (PMID 36854722, 2023). "Collectively, these results strongly imply that MESP2 can serve as a potential tumor suppressor in GC." (PMID 36854722, 2023). "In summary, we report that MESP2 functions as a completely new tumor suppressor in GC." (PMID 36854722, 2023).
MESP2 also shares sentences with these, for which no sentence is quoted: gastric cancer (1 paper); genetic disorder (1).